CXCL13 (C-X-C motif chemokine ligand 13)
Diseases named in the same sentence as CXCL13 in open-access papers (continued):
Sharing a sentence is not in itself a finding about the gene and the disease.
cancer (continued). "Based on these findings, CXCL13 might be a useful biomarker for determining the diagnosis and prognosis of human cancers and also a biomarker for evaluating the efficacy of immunotherapy." (PMID 35141160, 2022). "CXCL13 was significantly highly expressed in the cancer tissues of LUAD patients." (PMID 35844446, 2022). "Furthermore, our analysis showed that CXCL13 expression levels were positively related to immune-related genes in most cancers." (PMID 35141160, 2022). "Simultaneously, CXCL13 derived from cancer cells binding CXCR5 on T cells may enhance PD1/PD-L1 mediated exhaustion resulting in apoptosis of effector lymphocytes." (PMID 35392977, 2022). "Even though we used a wide panel of inflammatory cytokines, genetic instruments were not available for several additional cytokines that may be implicated in cancer, such as IL-13, IFN-gamma and CXCL13." (PMID 35012533, 2022). "CXCL13 mRNA expression in cancer tissue was lower than adjacent tissues in READ (p < 0.01)." (PMID 35141160, 2022). "CXCL13 may promote the occurrence, development and poor prognosis of cancer by activating other oncogenic pathways such as JAK-STAT and NF-KB pathways) through chemokine pathway or cytokine receptor pathway." (PMID 35141160, 2022). "We found that CXCL13 CNV affected clinical outcomes in 6 types of cancer." (PMID 35141160, 2022). "CXCL13 might be a useful biomarker for determining the diagnosis and prognosis of human cancers but also a biomarker for evaluating the efficacy of immunotherapy." (PMID 35141160, 2022). "Furthermore, we explored the correlation between CNV of CXCL13 and the overall survival of cancer patients." (PMID 35141160, 2022). "The prognosis of CXCL13 in different cancers is controversial." (PMID 35905218, 2022). "In cancers that CXCL13 harbor favorable prognosis, one study reported that CXCL13 was associated with better overall survival and positively correlated with infiltration of six immune cells (B cell, CD8+T cells, CD4+T cells, macrophages, neutrophils, dendritic cells) in SKCM." (PMID 35141160, 2022). "In addition, several studies have reported that CXCL13 modulates cancer stem cell properties by recruiting B-cells." (PMID 36248850, 2022). "However, gene knockdown evidence including the neutralization of overexpressed CXCL13 or CXCR5 activities has displayed the therapeutic potential of this important chemokine axis in numerous cancers." (PMID 36217194, 2022). "Oppositely, in cancers that CXCL13 harbor unfavorable prognosis, CXCL13 may promote tumors through chemokine signaling pathway, cytokine-cytokine receptor interaction and JAK-STAT signaling." (PMID 35141160, 2022). "In parallel, we investigated the role of CXCL13 in pan-cancer prognosis using the TCGA dataset." (PMID 35141160, 2022). "Taken together, we speculate that the high level of CXCL13 in cancer tissues of LUAD patients may be related to the activation and recruitment of B cells and T cells, and B cells and dendritic cells may be important sources of CXCL13." (PMID 35844446, 2022). "This suggests that CXCL13-producing CD8+ T cells could be players crucial for cancer immunity and would be targeted by checkpoint inhibition therapy." (PMID 35880181, 2022). "A close association was observed between CXCL13 and DNMT expression in 15 cancer types." (PMID 35141160, 2022). "Small G protein downstream kinases Rac and RhoA were determined upon cancer cells receiving CXCL13." (PMID 35053457, 2022). "The association between CXCL13 and MSI was significant in 9 cancer types." (PMID 35141160, 2022). "Although our study does not provide information on a functional role of CXCL13, linking elevated CXCL13 serum levels with impaired outcomes following the resection of BTC, our data suggest that high CXCL13 serum levels might reflect a more aggressive cancer." (PMID 36077611, 2022).
cancer (continued). "Similar to the pan-cancer analysis, LRP2 mutations had high TMB, MSI and immune cell infiltration in EC and also leaded to high expression of immune-related genes, such as CXCL9, CXCR6, CXCL13, ICOS and immune checkpoint genes (CTLA4 and LAG3)." (PMID 35834061, 2022). "Some of the significant cancer hallmark terms are epithelial-mesenchymal transition (MSX1, CXCL12, SCG2, SLIT2), KRAS signaling up (F13A1, ADAMDEC1), inflammatory response (CCL5, VIP), IL-6/JAK/STAT3 signaling (CXCL13)." (PMID 35486660, 2022). "CXCL13, a chemokine ligand for CXCR5 that is associated with B-cell recruitment, may be involved in cancer progression and has been shown to be overexpressed in oral SCC37,38." (PMID 33888854, 2021). "Whether CXCL13 measured from the serum alone can serve to track the formation of TLS in the context of immunotherapy in cancer awaits investigation." (PMID 34267760, 2021). "Recent studies proved that CXCL13 could control the cancer cell phenotype in various solid tumors and impact the migration, invasiveness, and growth of cancer cells." (PMID 33679883, 2021). "The endpoint of facilitating metastasis may arouse enthusiasm in pursuing CXCL13/CXCR5 as a potential target for cancer therapy." (PMID 34947813, 2021). "Here, we noticed that TOX has significant interactions with multiple key genes of exhausted T cell comprising PD‐1 (Cor = .11, P = .014), TIM‐3 (Cor = .18, P < .0001), TIGHT (Cor = .2, P < .0001) and CXCL13 (Cor = .16, P < .001), which play critical role on current cancer immunotherapy." (PMID 32700817, 2020). "The chemokine ligand CXCL13 and its chemokine receptor CXCR5 are among the key chemotactic factors that play crucial roles in the biology of cancer cells, and the CXCL13/CXCR5 signaling axis makes pivotal contributions to the development and progression of several human cancers." (PMID 33213490, 2020). "Ultimately, B cells and CXCL13 have great therapeutic potential for cancer treatments." (PMID 33193299, 2020). "In addition, multiples strategies are proposed for modulating the B cell-CXCL13 axis for cancer immunotherapies." (PMID 33193299, 2020). "The influence of cancer CXCL13 content on DDFS was most evident in the TNBC subset." (PMID 29482642, 2018). "CXCL13 could activate many signaling pathways in cancer cells through binding to its receptor CXCR5, a member of G protein coupled receptor (GPCR) superfamily." (PMID 30723697, 2018). "Previously studies revealed CXCL13 can regulate cancer cell migration and invasion." (PMID 28881808, 2017). "The results displayed that CXCL13 protein expression was significantly higher in cancer tissues than that of their corresponding adjacent normal tissues (P = 0.015) and significantly up-regulated in young patients’ tissues relative to older counterparts (P = 0.041)." (PMID 25990390, 2015). "Furthermore, it is essential to acknowledge that CXCL13 might facilitate the onset, progression, and adverse prognosis of cancer by triggering additional oncogenic pathways, like the JAK-STAT pathway, via the chemokine pathway or cytokine receptor pathway." (PMID 38459390, 2024). "It is noteworthy that the secretion of chemokine CXCL13 can induce the expression of lymphotoxin-α1β2 (LTα1β2) on B cells or LTi cells through the CXCL13-CXCR5 axis and form a positive feedback loop, driving the expansion of stromal cells such as cancer-associated fibroblasts (CAFs) and TLSs." (PMID 39456558, 2024). "Therefore, we hypothesise that strategies to enrich CD8_C8_CXCL13 T cells and engineer TCRs from both CD8_C8_CXCL13 and CD8_C11_HAVCR2 T cells could enhance the efficacy of adoptive T cell therapy in cancer treatment." (PMID 39231979, 2024). "In addition, cancer cells that produce B cell chemoattractants like C-X-C motif chemokine ligand 13 (CXCL13) may also play an important role in attracting B cells to the microenvironment." (PMID 36831506, 2023). "However, CXCL13+ T cells showed a wider distribution in cancer tissues." (PMID 37675100, 2023).
cancer (continued). "As CXCL13-positive CD8-positive T cells have been strongly linked to patient response to anti-PD1 immune checkpoint blockade, combinatorial TIM-3 and PD-1 blockade therapy may be of interest for the (re)activation of anti-cancer immunity in EOC." (PMID 36341460, 2022). "Notably, upon combination therapy, ASPH-MYC and downstream PD-L1/PD-1 signals were blocked; CTLs secreted CXCL13 could bind to CXCR5 on cancer cells and produce cytotoxicity against them efficiently." (PMID 35392977, 2022). "However, the potential roles CXCL13 plays in cancer metabolism remain to be investigated." (PMID 34947813, 2021). "Therefore, the CXCL13/CXCR5 axis plays a key role in regulating the proliferation of many cancer cells and could be a valuable therapeutic target." (PMID 34947813, 2021). "In contrast, the expression of genes regulating immune cell trafficking (e.g., CXCL13, CXCL9, XCL2, CCL5), T-cell activation and clonal expansion (e.g., CD27, CD28, ICOS, IL21, IL2) were massively decreased in 9p21-loss tumors across multiple cancer types/subtypes." (PMID 34556668, 2021). "Similarly, there are opposite opinions or data about the role of CXCL13 in cancer." (PMID 25990390, 2015). "What might the biological role of CXCR5/CXCL13 interactions be in the case of human cancers?" (PMID 18781150, 2008). "In contrast, enhanced clonality was evident for CD4+ CXCL13+ Tfh cells and CD8+ CXCL13+ T cells in ICB-Rs, showing distinctive TCR dynamics at play in the ICB response to cancer." (PMID 40054456, 2025). "The mRNA expression profile of six Tex markers, LAG-3, PDCD1, TIGIT, HAVCR2, CXCL13, and LAYN was investigated in pan-cancer." (PMID 40076932, 2025). "Identification of CXCL13 + CD8 + -centred immune responses and immune-cold cancer cells after anti-PD-L1-CRT therapy holds promise for future developments in treatment strategies." (PMID 40670667, 2025). "We identified CXCL13 + CD8 + T cells expressing GMZB and IFNG—cytotoxic T lymphocytes (CTLs)—as the cells that attack cancer cells following PD-L1-CRT." (PMID 40670667, 2025). "Researchers transplanted collagen sponge scaffolds containing LTα1β2, CCL19, CCL21, CXCL12, CXCL13, and soluble RANK ligands, which over time resulted in the development of immune-competent artificial TLSs with potential applications for cancer treatment." (PMID 39840050, 2024). "We investigated the methylation levels (beta values) of TIGIT, CXCL13, LAYN, LAG3, PDCD1, and HAVCR2 across different cancer types." (PMID 39064019, 2024). "Among the pivotal chemotactic factors, CXCL13 and CXCR5 assume critical roles in shaping the biology of cancer cells." (PMID 38459390, 2024). "Visible differences were observed between different cancer stages in KIRP, according to CXCL13 mRNA levels." (PMID 39064019, 2024). "CXCL13 is a signaling molecule that binds to its receptor, CXCR5, and is known to be involved in several cancer‐related pathways." (PMID 39344390, 2024). "Conversely, when PD‐1 blockade was combined with this λ phage vaccine, the CXCL13/CXCR5 axis contributes to TLS formation and promotes the cytotoxic effect of CTL on cancer cells." (PMID 38469550, 2024). "Lymphotoxin-producing Breg cells can be recruited by CXCL13, which stimulate the lymphotoxin receptor on cancer cells, induce IKKα nuclear translocation and STAT3 activation, and promote cancer metastasis." (PMID 37868967, 2023). "The strength of this association was confirmed when a recent meta-analysis, of published single-cell data for CXCL13+ CD8+ T cells, found their presence correlated with improved responsiveness to checkpoint therapy across all cancers tested." (PMID 37520560, 2023). "Aberrantly active CXCL13/CXCR5 signaling promotes cancer cell growth through complex molecular mechanisms in breast, intestinal, and lung cancers." (PMID 37503314, 2023). "CXCL13-producing PD-1hiCD8+ T cells and bystander CD8+ T cells in close proximity to the CD20+ B cell zones of TLSs can detect a broad spectrum of cancer-irrelevant epitopes." (PMID 37868967, 2023).
cancer (continued). "In specific, TIS is referred to as an 18‐gene signature (CCL5, GZMK, CD3D, CD3E, CD2, HLA‐DRA, IL2RG, NKG7, CIITA, CXCR6, LAG3, TAGAP, HLA‐E, CXCL13, IDO1, CXCL10, STAT1, and GZMB), which was related to the response to ICIs in various cancers." (PMID 37434432, 2023). "This was associated with the reduced expression of the key regulators of B cell chemotaxis, Cxcl12 and Cxcl13 by both the HFD and the cancer cells." (PMID 38264656, 2023). "This is mirrored by a decrease in Cxcl13, a potent B cell chemoattractant which was reduced by the HFD but more so by the cancer cell presence." (PMID 38264656, 2023). "The CXCL13/CXCR5 signal axis plays a vital role in the occurrence and development of several human cancers." (PMID 35898471, 2022). "The results also suggested a correlation between CXCL13 expression levels and TMB in 11 cancer types." (PMID 35141160, 2022). "CXCL13 and its chemokine receptor 5 (CXCR5) are among the key chemotactic factors which play crucial roles in deriving cancer cell biology." (PMID 35432485, 2022). "The PD-1+ TILs that secreted CXCL13 and avidly interacted with CXCR5+PD-L1+ cancer cells were predominant in controls." (PMID 35392977, 2022). "We also summarize recent preclinical and clinical evidence regarding the ICI-therapeutic implications of targeting the CXCL13/CXCR5 axis and discuss the potential role of this signaling pathway in cancer immunotherapy." (PMID 35053457, 2022). "Asbestos can induce inflammatory changes, including increase in MMP7, CXCR5, CXCL13, and CD44, and this chronic inflammation can lead to chronic diseases, such as cancer." (PMID 35036082, 2022). "In the top 20 upregulated DEGs of lymph node‐derived exhausted CD8+ T cells, CXCL13, CXCR4, CH25H, HSPD1, HSP90AA1, and ATF3 have been confirmed to promote lymph node metastasis in several cancer types." (PMID 35184420, 2022). "QRT-PCR was used to validated the cancer tissues and paracancer tissues differences of CXCL13 expression in STAD and COAD and the correlation between CXCL13 and immune genes in STAD." (PMID 35141160, 2022). "However, CXCL13 expression-based panoramic picture in pan-cancer remain unclear." (PMID 35141160, 2022). "In cancers that CXCL13 harbor unfavorable prognosis, such as KIRC, intratumoral CXCL13 + CD8 + T cell infiltration determines poor clinical outcomes and immunoevasive contexture." (PMID 35141160, 2022). "CXCL9, CXCL10, CXCL11, CXC12, CXCL13, and CXCL14 expression in the tissue adjacent to carcinoma was significantly different." (PMID 35181719, 2022). "CXCL13 and CXCR5 have important roles in cancer and represent potential markers to predict the response to immune checkpoint therapy." (PMID 34947813, 2021). "TLS in other cancers have been identified and defined by expression of a number of chemokines that are involved in TLS neogenesis: CCL19, CCL21, CXCL12, CXCL13, CCL17, and CCL22." (PMID 34943886, 2021). "We found that, compared with normal tissues, the TIMP1 protein was expressed highly and significantly in cancer samples, while the ITLN1, TSPAN11, CPRC5B, and CXCL13 proteins were expressed poorly in cancer samples." (PMID 33579281, 2021). "The CXCL13 and chemokine receptor 5 (CXCR5) signaling axis has a key role in the occurrence and development of several human cancers." (PMID 33579281, 2021). "It has been widely reported that the CXCL13/CXCR5 axis activates the canonical NFκB pathway and amplifies inflammatory responses in several cancer cells." (PMID 33213490, 2020). "To summarize, CXCL13 and its receptor CXCR5 have emerged as key players of cancer initiation and progression." (PMID 31354634, 2019). "Exposure of CXCR4+CXCR7+ cancer cells to CXCL12 greatly potentiated their TEM towards the chemokines CCL19 and CXCL13." (PMID 21672222, 2011).
cancer (continued). "This trend of CXCL13 + CD8+ cells engaging directly with cancer cells, as opposed to CXCL13 − CD8+ cells, was further validated through region stratification analysis across all examined fields." (PMID 40670667, 2025). "CXCL13 promotes B cell infiltration into tumors and is crucial for TLS development, with its density serving as a favorable prognostic indicator for immunotherapy response in various cancers." (PMID 40287532, 2025). "Therefore, further investigation with large-scale cohort studies across the diverse types of irAEs, cancers, and regimens will be necessary to validate the importance of ICOS+CD4+ T cells and CXCL13 in irAE development." (PMID 40198121, 2025). "We speculate that RANBP17 may suppress stromal CXCL13, CCL19 and CCL21 through exosome‐mediated mechanisms by reprogramming the cargo of cancer‐derived exosomes to include regulatory RNAs and proteins." (PMID 41397929, 2025). "This novel approach revealed dynamic, preferential cancer cell invasion within specific anatomical regions of LNs, particularly the subcapsular sinus (SCS) and cortex, as well as chemokine-rich domains of immobilized CXCL13 and CCL1." (PMID 40109746, 2025). "Furthermore, in all three post-PD-L1-CRT tissue samples, we confirmed that CXCL13 + CD8+ lymphocytes expressed GZMB and directly interacted with cancer cells at the single-cell resolution." (PMID 40670667, 2025). "Finally, we analysed CXCL13 + CD8 T cells, which are effector cells, and immune-cold cancer cells on a cell-by-cell basis via “single-cell analysis”." (PMID 40670667, 2025). "Previous studies have indicated efficacy correlation of CCR8+ Treg cells and CXCL13+ Tex cells with immunotherapy in multiple cancer types;27,28 we therefore matched the infiltration ratio or TCR clonal expansion of CCR8+ Treg cells and CXCL13+ Tex cells with stratified clinical efficacy." (PMID 38897205, 2024). "For immune-related genes, the expression of genes involved in the categories of tight junction such as MYH11, PPP2R2C, and MYL9, cancer development such as TAGLN and CALD1, and acquired immunity such as PCP4 and CXCL13 was upregulated in the LP group when compared with that in the CON group." (PMID 37731924, 2023). "In addition to CD4+ Tfh and CD8+ Tex subsets, CXCL13+ T cells also had a high proportion in Th17 and CD8+ Tem subsets in cancer tissues." (PMID 37675100, 2023). "It is reported that CXCL13 could be expressed by immunosuppressive cytokine, TGF‐ ß, produced by macrophages as a result of cancer‐induced chronic inflammation." (PMID 36453453, 2023). "With regard to cancer immunology, significantly higher CXCL13 mRNA expression was detected in draining compared to non-draining LN." (PMID 36836910, 2023). "In addition, the proportion of CXCL13+CD39+CD8+ TILs in pTRT cell-high BrM was similar to that in primary NSCLC, one of the most responsive cancers to ICB53." (PMID 37217652, 2023). "Direct binding of GR is observed at the CXCL13 gene promoter and nearby the gene locus at putative enhancers, which are conserved across multiple cell lines, including the B cell line Nalm6, the monocyte cell line THP1, and cancer cell lines." (PMID 37149682, 2023). "Moreover, in cancer-induced bone pain, inhibition of CXCL10, CXCL11 and CXCL13 enhanced morphine analgesic properties in rats." (PMID 36618360, 2022). "An increasing number of studies have identified the influence of CXCL13 on prognosis in patients with cancer, regardless of the use of immunotherapy treatment." (PMID 35053457, 2022). "In this review, therefore, we discuss the CXCL13/CXCR5 axis and summarize its mechanism of action in cancer cells and lymphocytes, its contributions to immunity and cancer pathobiology, and its role in response to immunotherapy and potential to serve as a biomarker." (PMID 35053457, 2022). "In addition, S1P/CXCL13 regulates VEGF, which is involved in FAK phosphorylation, leading to cell migration and invasion in cancer." (PMID 36500220, 2022).